ARPC1B (actin related protein 2/3 complex subunit 1B)
Diseases named in the same sentence as ARPC1B in open-access papers (continued):
Sharing a sentence is not in itself a finding about the gene and the disease.
glioma (5 papers, 2022 to 2025). A benign or malignant brain and spinal cord tumor that arises from glial cells (astrocytes, oligodendrocytes, ependymal cells). "Their downstream ARPC1B, crucial in glioma‐associated macrophages, facilitated glioma cell migration, invasion, epithelial‐mesenchymal transition, and fostered an immunosuppressive microenvironment, mirroring our findings." (PMID 39753851, 2025). "The higher expression of ARPC1B is associated with a progressive malignancy through macrophage recruitment, EMT, invasion, or migration of glioma cells." (PMID 39012280, 2024). "The signaling between the macrophages and glioma cells is evident through ARPC1B by the IFNγ-IRF2-ARPC1B axis." (PMID 39012280, 2024). "ARPC1B has been found to promote radiotherapy resistance and maintenance of the mesenchymal phenotype in glioma stem cells." (PMID 37304283, 2023). "The overexpression of ARPC1B in glioma cells has been shown to maintain the malignant phenotype, including migration, invasion, and epithelial-to-mesenchymal transition (EMT) status." (PMID 37304283, 2023).
actinopathies (4 papers, 2021 to 2022). "Recently described IEIs associated with allergic inflammation such as T-bet deficiency caused by TBX21 variants, or the actinopathy ARPC1B deficiency, are therefore not captured in this study." (PMID 35273610, 2022).
combined immunodeficiency (4 papers, 2021 to 2025). A broad classification of inherited disorders presenting at birth that affect both the cell-mediated and humoral aspects of the immune response. "This was determined in patients with combined immunodeficiency (CID) that have a homozygotic mutation in the gene ARPC1B, which results in a defect in the development of the T cell IS." (PMID 35371070, 2022).
vasculitis (3 papers, 2021 to 2025). "A homozygous complex frameshift mutation in ARPC1B was identified in a 7-year-old Moroccan boy who presented with a novel combined immunodeficiency involving recurrent infections, mild bleeding tendency, vasculitis (including leukocytoclastic vasculitis), and allergic reactions." (PMID 34621800, 2021).
glioblastoma (2 papers, 2025). The most malignant astrocytic tumor (WHO grade IV). "Therapeutic targeting of ARPC1B in ccRCC is mechanistically supported by preclinical evidence from glioblastoma, where its modulation enhances radiotherapy sensitivity and synergizes with immune checkpoint inhibitors to augment antitumor immunity." (PMID 41050079, 2025). "In addition, ARPC1B promotes radiotherapy resistance in glioblastoma, and high expression of ARPC1B indicates poor prognosis." (PMID 40903212, 2025).
inflammatory bowel disease (2 papers, 2024 to 2025). A spectrum of small and large bowel inflammatory diseases of unknown etiology. "Notably, the impaired Arp2/3 actin filament branching, due to Arpc1B deficiency, is associated with platelet abnormalities, recurrent invasive infections, inflammatory bowel disease, and T-cell cytoskeletal defects." (PMID 39349750, 2024).
IPEX syndrome (2 papers, 2021 to 2025). "While present in almost all categories, their burden and distribution vary, with certain defects acting as clear ‘hotspots’, such as IPEX syndrome, APECED, LRBA, RAG1, RAG2, CD3γ, Helios, ARPC1B, and CD55 deficiencies." (PMID 41394846, 2025).
lymph node metastasis (2 papers, 2023 to 2025). "Clinically, the association between ARPC1B overexpression and lymph node metastasis (p = 0.029) underscores its relevance to advanced disease management." (PMID 41050079, 2025). "The expression of ARPC1B increased with increase in staging and grading, lymph node metastasis, and distant metastasis." (PMID 37795220, 2023). "Then, we found that ARPC1B expression increased with increase in staging and grading, and lymph node metastasis and distant metastasis." (PMID 37795220, 2023).
oral squamous cell carcinoma (2 papers, 2021 to 2022). "In terms of tumors, ARPC1B was identified as a prognostic marker in oral squamous cell carcinoma and melanoma." (PMID 36081667, 2022). "ARPC1B can be used not only as a predictive biomarker for assessing the sensitivity of UM to radiotherapy but also as a prognostic biomarker for oral squamous cell carcinoma." (PMID 34630418, 2021).
Pancreatic Cancer (2 papers, 2011 to 2025). "ARPC1B+ cancer stem cells (CSCs) in pancreatic cancer are identified as a subpopulation resistant to gemcitabine." (PMID 40903212, 2025). "In our study, we found ARPC1B is significantly upregulated in gemcitabine‐resistant CSCs compared to non‐resistant CSCs, and it is also significantly elevated in pancreatic cancer samples versus normal tissues." (PMID 40903212, 2025). "In conclusion, our study advances the understanding of the role of ARPC1B+ CSCs in pancreatic cancer chemoresistance." (PMID 40903212, 2025). "Subsequently, we analysed the overall survival of pancreatic cancer patients based on multiple dimensions, including the degree of gemcitabine resistance, tumour stemness, and ARPC1B expression levels." (PMID 40903212, 2025). "Subcutaneous and orthotopic pancreatic tumour models, and PDOs in the combination‐treated group were markedly smaller than those in the control or gemcitabine‐alone groups, which demonstrated that targeting ARPC1B+ CSCs by CK‐636 can sensitise pancreatic cancer to gemcitabine." (PMID 40903212, 2025). "Additionally, exploring the combination of ARPC1B‐targeted therapies with other treatment modalities, such as immunotherapy or targeted therapy, may offer synergistic benefits in treating pancreatic cancer." (PMID 40903212, 2025).
prostate carcinoma (2 papers, 2022 to 2023). A carcinoma that arises from epithelial cells of the prostate gland. "Recent studies have demonstrated that ARPC1B promotes cancer cell invasion and metastasis in several types of cancer, including glioblastoma and prostate cancer." (PMID 37304283, 2023). "On the other hand, knockdown of ARPC1B in prostate cancer cells has been observed to reduce the proliferation, migration, and invasion and cause cell cycle arrest at the G2/M phase via the downregulation of AURKA." (PMID 37304283, 2023). "Additionally, we confirmed the prognostic significance of ARPC1B genomic alteration using two cohorts in the TCGA public database for overall prostate cancer and bladder cancer disease progression." (PMID 35163398, 2022). "Therefore, the role of ARPC1B and its correlation with ERG gain and PTEN loss can have an association on cell migration and invasion, which may promote the progression of invasive prostate cancer." (PMID 35163398, 2022).
viral infections (2 papers, 2019 to 2021). "Similarly, NK cells of ARPC1B-deficient patients show migration defects and NK-cell dysfunction, which may contribute to the predisposition to viral infections." (PMID 33679784, 2021).
Wiskott-Aldrich syndrome (2 papers, 2019 to 2025). Wiskott-Aldrich syndrome (WAS) is a primary immunodeficiency disease characterized by microthrombocytopenia, eczema, infections and an increased risk for autoimmune manifestations and malignancies. "Recently, several groups have described ARPC1B deficiency, an autosomal recessive form of CID associated with immune dysregulation and platelet abnormalities that resemble what observed in Wiskott-Aldrich syndrome (WAS)." (PMID 31440487, 2019).
brain inflammation (1 paper, 2022). "The ARPC1B cluster may be involved in the cytolytic activity of CD8 cytotoxic T lymphocytes, which is related to brain inflammation." (PMID 36414996, 2022).
breast cancer (1 paper, 2019). A primary or metastatic malignant neoplasm involving the breast. "Among all genes encoding Arp2/3 subunits, ARPC1B overexpression in tumours is associated with the poorest metastasis-free survival in breast cancer patients." (PMID 30971746, 2019).
diabetes (1 paper, 2025). "These insights emphasize the potential novel link between ARPC1B regulation of kidney stones and diabetes metabolism." (PMID 40718484, 2025). "ARPC1B’s effects on diabetes are not limited to immune responses; studies have shown that ARPC1B is a substrate of PAK1 during mitosis, and changes in PAK1 levels regulate the tissue crosstalk of pancreatic β cells, affecting systemic glucose homeostasis." (PMID 40718484, 2025). "Western blotting further confirmed that the protein levels of S100A4, ARPC1B, and CEBPD were significantly upregulated.These results collectively suggest that S100A4, ARPC1B, and CEBPD may serve as core biomarkers in the common mechanisms underlying diabetes and kidney stones." (PMID 40718484, 2025). "One of the strengths of this study is the identification of three novel biomarkers for diabetes and kidney stones using machine learning methods: S100A4, ARPC1B, and CEBPD." (PMID 40718484, 2025). "Among 101 machine learning models, S100A4, ARPC1B, and CEBPD were identified as the most significant interacting genes linking diabetes and kidney stones." (PMID 40718484, 2025). "The mechanisms of S100A4, ARPC1B, and CEBPD in kidney stones and diabetes should be further explored in wet lab experiments." (PMID 40718484, 2025). "We identified three biomarkers—S100A4, ARPC1B, and CEBPD—that may play critical roles in the shared pathogenesis of diabetes and kidney stones." (PMID 40718484, 2025). "Overall, our study suggests that S100A4, ARPC1B, and CEBPD may serve as valuable biomarkers that play a crucial role in the shared pathogenesis of kidney stones and diabetes." (PMID 40718484, 2025).
head-neck cancer (1 paper, 2019). "Co-expression analyses indicated that SPP1 was co-expressed with MMP9, ARPC1B, and APP in head-neck cancer." (PMID 31849319, 2019). "The results showed that SPP1 was over-expressed in patients with head-neck cancer, and the top 3 genes co-expressing with SPP1 were Matrix Metallopeptidase 9 (MMP9), Actin Related Protein 2/3 Complex Subunit 1B (ARPC1B) and Amyloid Beta Precursor Protein (APP)." (PMID 31849319, 2019).
Hyperammonemia (1 paper, 2023). An increased concentration of ammonia in the blood. "Shared DAP that were increased at both 6 and 24 h of hyperammonemia included Eif4b, Map4, Arpc1b, Eif3b, S100a4, Smad4, and Hist1h2bb." (PMID 37101412, 2023).
infertile (1 paper, 2017). "Additionally, the Arpc1b gene was up-regulated in Bcl6b, Etv5, Pouf31 and Dazap1 KD, and Alcam was up-regulated in Bcl6b, Etv5, Pouf31 and Ing2 KD infertile mice." (PMID 29150651, 2017).
kidney stones (1 paper, 2025). "We found that after kidney stone treatment, the expression of S100A4, ARPC1B, and CEBPD genes in diabetic mice was significantly elevated." (PMID 40718484, 2025).
lymphopenia (1 paper, 2019). Reduction in the number of lymphocytes. "We propose that loss of surface GLUT1 would likely contribute to the CD8 lymphopenia in the ARPC1B-deficient patient." (PMID 31710310, 2019).
nephrotic syndrome (1 paper, 2016). A collection of symptoms that include severe edema, proteinuria, and hypoalbuminemia; it is indicative of renal dysfunction. "It has been reported that OSGEP and TP53RK, both of which are implicated in nephrotic syndrome with primary microcephaly, interact with components of the ARP2/3 complex including ARPC1B involved in actin remodeling at lamellipodia." (PMID 29333229, 2016).
Parkinson disease (1 paper, 2019). A progressive degenerative disorder of the central nervous system characterized by loss of dopamine producing neurons in the substantia nigra and the presence of Lewy bodies in the substantia nigra and locus coeruleus. "Moreover, ARPC1B-deficient patients do not exhibit symptoms of spastic paraplegia or Parkinson’s disease, due to mutation in the strumpellin subunit of the WASH complex and mutation in the VPS35 subunit of the retromer complex, respectively." (PMID 31710310, 2019).
periodontitis (1 paper, 2022). An acute or chronic inflammatory process that affects the tissues that surround and support the teeth. "During the inflammatory response of periodontitis, the lymphocytes, macrophage and neutrophils are regulated by expression of multiple genes, such as ARHGAP10, ARPC1B, DOCK1, FGF2/4, TNFRSF1B, NXT1, and AHR, all of which were identified in our analysis." (PMID 35491409, 2022).
type 2 diabetes (1 paper, 2022). "We found that the abundances of PAK1 protein and its downstream effector in muscle, ARPC1B, are significantly reduced in the skeletal muscle of humans with type 2 diabetes, compared to the non-diabetic controls, making skeletal muscle PAK1 a candidate regulator of glucose homeostasis." (PMID 35222279, 2022).
uveal melanoma (1 paper, 2025). A melanoma derived from melanocytes of the uveal tract. "In the uveal melanoma cohort, a six‐molecule signature (ARPC1B, BTBD6, GUSB, KRTCAP2, RHBDD3, and SLC39A4), which was associated with glycolysis and the immune response, was established and used for survival prediction and risk stratification of these patients." (PMID 39830021, 2025).
Zika virus infection (1 paper, 2016). "The novel interactions of FNDC3B with IFITM3 and SPTA1, ARPC1B and AGTR2 with IFITM1 may shed light on mechanisms of host invasion underlying cytoskeletal re-arrangements that follow Zika virus infection." (PMID 29333229, 2016).
tumor (16 papers, 2011 to 2025). "Since ARPC1B is closely associated with GBM phenotypes, we performed a tumor sphere formation assay and limiting dilution assay to evaluate the function of ARPC1B on GSC biology." (PMID 36380368, 2022). "Moreover, the correlation between ARPC1B expression and higher mutation burden and intra‐tumour heterogeneity further interprets its significance in chemoresistance." (PMID 40903212, 2025). "Consistent with in vitro findings, xenograft tumor tissues from ARPC1B-knockdown groups exhibited significantly reduced protein levels of β-catenin, p-GSK3β, c-Myc, and cyclin D1 (p < 0.05)." (PMID 41050079, 2025). "Collectively, our findings provide compelling evidence highlighting ARPC1B as a vital regulator of ccRCC tumor progression." (PMID 41050079, 2025). "ARPC1B's biological functions in CSCs and their interactions or communications with other cells within the tumour microenvironment need further investigation." (PMID 40903212, 2025). "IHC analysis confirmed reduced staining of these proteins in ARPC1B-knockdown tumor tissues relative to NC controls (Fig. A9)." (PMID 41050079, 2025). "Recent investigations have underscored ARPC1B as a significant contributor to tumor progression, particularly in promoting invasion and metastasis, and associated its elevated expression with unfavorable prognoses in multiple cancer types." (PMID 41050079, 2025). "Elevated ARPC1B was identified in 57 (38%) of the tumor samples, significantly higher compared to only 4 cases (13%) in matched non-tumorous tissues (OR = 0.2510; 95% CI: 0.09093–0.7292; p = 0.009; Fig. A2)." (PMID 41050079, 2025). "Immunohistochemistry (IHC) further demonstrated reduced ARPC1B expression and diminished Ki-67 staining in ARPC1B-silenced tumors, indicating decreased tumor cell proliferation (Fig. A6)." (PMID 41050079, 2025). "In our in vivo and ex vivo experiments, the combination of gemcitabine and CK‐636, a compound identified through molecular docking analysis and SPR analysis as a potential ARPC1B‐targeting agent, demonstrated remarkable synergy in anti‐tumour efficacy." (PMID 40903212, 2025). "Taken together, these findings strongly support that ARPC1B knockdown significantly reduces tumor growth, tumor mass, and proliferation in vivo, highlighting its critical contribution to ccRCC progression." (PMID 41050079, 2025). "ARPC1B expression exhibited significant relationships with clinical parameters, particularly tumor stage (T stage; p = 0.003) and Fuhrman grading (p < 0.001)." (PMID 41050079, 2025). "The ARPC1B+ CSC cell population exhibited unique tumour function enrichment compared to other cell populations, such as mitotic spindle, epithelial‐mesenchymal transition, TGF‐β signalling, apical junction, and KRAS signalling up." (PMID 40903212, 2025). "Elevated ARPC1B expression correlates significantly with aggressive tumor phenotypes, poor clinical outcomes, and activation of key oncogenic signaling pathways, specifically EMT and Wnt/β-catenin." (PMID 41050079, 2025). "At a mechanistic level, our data underscore that ARPC1B promotes ccRCC advancement through stimulation of EMT, an essential mechanism underlying tumor invasion and metastatic capability." (PMID 41050079, 2025). "This study aims to investigate the clinical significance of ARPC1B expression in ccRCC and elucidate its functional contributions to tumor progression." (PMID 41050079, 2025). "IHC analysis corroborated these findings, with reduced staining intensity for mesenchymal markers (Vimentin, N-cadherin, ZEB-1) and increased intensity for E-cadherin observed in ARPC1B-knockdown tumor tissues (Fig. A7C)." (PMID 41050079, 2025). "At the conclusion of experiments, tumor weights were significantly lower in ARPC1B-knockdown groups relative to NC groups (p < 0.001 for 786-O; p < 0.05 for Caki-1)." (PMID 41050079, 2025). "Tumor volume monitoring over 12 days revealed significantly suppressed tumor growth in ARPC1B-knockdown groups (p < 0.001)." (PMID 41050079, 2025).